CHD7 (chromodomain helicase DNA binding protein 7)
Diseases named in the same sentence as CHD7 in open-access papers (continued):
Sharing a sentence is not in itself a finding about the gene and the disease.
CHARGE syndrome (continued). "Finally, molecular genetic testing by whole exome sequencing of the neonate and her parents revealed a novel de novo heterozygous frameshift c.3506_3509dup variant in the CHD7 gene, confirming the clinical diagnosis of CHARGE syndrome." (PMID 33671041, 2021). "Notably, OTX2 has been linked to CHD7 in pathogenetic mechanisms common to both KS and CHARGE syndromes as well as cerebellar development." (PMID 33869187, 2021). "Besides CHH and CHARGE syndrome related symptoms, CHD7 variants can also lead to other CHD7-related manifestations, including abnormalities of the skeleton, muscle, skin, digestive system and urinary system." (PMID 35047002, 2021). "This study supports the hypothesis that CHD7 haploinsufficiency is the main cause of CHARGE syndrome." (PMID 34616726, 2021). "It was recently reported that CHARGE syndrome is caused by mutations in the CHD7 gene." (PMID 34563184, 2021). "These facts suggest that homozygous mutations in CHD7 might cause embryonic lethality, possibly due to the wide expression of the CHD7 gene in tissues affected in CHARGE syndrome." (PMID 34616726, 2021). "It has been estimated that inherited and de novo CHD7 mutations account for 5–10 percent of all cases of KS and an accountable number of these patients exhibit mild form features of CHARGE syndrome, such as abnormally shaped ears, hearing loss, hare lip/cleft palate and cardiac abnormalities." (PMID 32982993, 2020). "CHD7 is a gene, mapping on the 8q12.2 chromosome, associated with the CHARGE syndrome." (PMID 33076341, 2020). "Indeed, pSAD-based minigenes have constituted an invaluable technology to functionally test variants of other disease genes such as GRN (Frontotemporal Dementia), SERPINA1 (Severe alpha-1 antitrypsin deficiency) and CHD7 (Charge Syndrome) genes." (PMID 31191615, 2019). "Previous studies have reported that mutations in CHD7 are the major cause of CHARGE syndrome." (PMID 29434620, 2018). "CHD7 mutations in typical CHARGE syndrome patients occur de novo in the vast majority of the cases." (PMID 29434620, 2018). "Heterozygous mutation of the CHD7 gene causes a severe congenital disease known as CHARGE syndrome." (PMID 29033785, 2017). "As CHD7 co‐factors and target genes are highly context‐dependent, the identity of these disease modifiers are likely to be distinct for each of the different phenotypes associated with CHARGE syndrome (Basson & van Ravenswaaij‐Arts, 2015)." (PMID 29168327, 2017). "In humans, CHD7 has been identified as the primary causative gene in the development of CHARGE syndrome, a complex disorder of multiple birth defects varying in severity and presentation, with up to 80% of patient cohorts presenting with a heterozygous loss-of-function mutation in the gene." (PMID 28280001, 2017). "Notably, de novo heterozygous mutations of the CHD7 gene are the primary cause of the CHARGE syndrome." (PMID 28649742, 2017). "Importantly, loss‐of‐function mutations of CHD7 are also associated with CHARGE syndrome (OMIM 214800), which is characterized, as in the case of CSS, by multiple congenital anomalies, including microphthalmia." (PMID 28608987, 2017). "However, in contrast to the most prevalent loss‐of‐function mutation of CHD7, such as nonsense mutation and frameshift deletion or insertion in CHARGE syndrome, the most frequent (86%) CHD7 mutations in human cancers were missense mutations." (PMID 28649742, 2017). "Based on the hypothesis that KS and nIHH may be a milder allelic variant of CHARGE syndrome, CHD7 was screened in 197 patients with KS or nIHH but devoid of CHARGE features." (PMID 29280744, 2017). "In contrast, more than 70% of CHD7 mutations in Kallmann syndrome are missense mutations, which correlate with mild phenotypes in these patients as compared to CHARGE syndrome." (PMID 29033785, 2017).
CHARGE syndrome (continued). "As a first step toward identifying the neuroanatomical alterations that may underlie the neurological deficits in CHARGE syndrome, we recently reported cerebellar hypoplasia in 35% of patients with CHD7 mutations." (PMID 28165338, 2017). "The discovery of loss‐of‐function mutations in the CHD7 gene in patients with CHARGE syndrome, has led to significant progress in elucidating the developmental and molecular genetic mechanisms underlying specific phenotypes associated with CHARGE syndrome (Layman, Hurd, & Martin, 2010)." (PMID 29168327, 2017). "Mutations in CHD7 are known to be closely linked to CHARGE syndrome (Coloboma, Heart defects, Atresia of the choanae, Retardation of growth and development, Genital hypoplasia, and Ear abnormalities, including deafness and vestibular disorders), also known as multiple congenital abnormality." (PMID 27955690, 2016). "CHARGE syndrome, which is a pattern of congenital anomalies, including eye, nose, ear, heart, and genital defects, as well as tibial hemimelia is a mutation of the CHD7 gene (chromodomain helicase DNA-binding protein 7), located on chromosome 8q." (PMID 27909860, 2016). "Mutations of CHD7 are the major cause for the CHARGE syndrome." (PMID 27585840, 2016). "Located in 8q12.2, CHD7 gene encodes a DNA-binding protein that acts as a positive transcriptional regulator by binding to enhancer elements in the nucleoplasm, and its disruption leading to Kallmann syndrome or CHARGE syndrome (OMIM# 214800)." (PMID 27699475, 2016). "Haploinsufficiency for CHD7 causes human CHARGE syndrome in over 90% of clinical cases." (PMID 26102480, 2015). "However, we begin with the clinical data obtained from patients and summarise our current knowledge of CHD7 mutations that cause CHARGE syndrome." (PMID 26411921, 2015). "As CHD7 haplo‐insufficiency is associated with a range of cognitive disabilities in CHARGE syndrome, our observations may have implications for understanding the basis of these deficits." (PMID 25183173, 2015). "Following this guideline, Bergman and colleagues performed the CHD7 analysis in a cohort of 36 Dutch KS patients (previously excluded to carry mutations in FGFR1, PROK2, PROKR2, and FGF8), identifying 3 heterozygous CHD7 mutations in patients having same features of CHARGE syndrome." (PMID 25254043, 2014). "Kis is the homolog to human CHD7, which is mutated in CHARGE syndrome." (PMID 25412171, 2014). "Mutations in CHD7, the gene responsible for CHARGE syndrome, were found in a heterozygous condition in a minority of KS patients and it has been suggested that KS may be a mild allelic variant of CHARGE syndrome." (PMID 23997646, 2013). "Finally, we report cerebellar vermis hypoplasia in 35% of CHARGE syndrome patients with a proven CHD7 mutation." (PMID 24368733, 2013). "Mutations in CHD7 are found in more than 60% of the patients with typical CHARGE syndrome." (PMID 24204987, 2013). "Otitis media can occur in normal individuals with no other symptoms or syndromes, but it is often seen in individuals clinically diagnosed with genetic diseases such as CHARGE syndrome, a complex genetic disease caused by mutation in the Chd7 gene and characterized by multiple birth defects." (PMID 22539951, 2012). "Heterozygosity for nonsense, deletion or missense CHD7 mutations is estimated to occur in 60–80% of patients with CHARGE syndrome; these mutations are distributed throughout the coding sequence and do not appear to be correlated with specific aspects of the clinical phenotype." (PMID 22363697, 2012).
CHARGE syndrome (continued). "Therefore, in this study, we have performed CHD7 mutational analysis in Korean patients with CHARGE syndrome presenting with profound hearing loss and typical inner ear malformations in order to broaden the genotypic spectrum of CHARGE syndrome." (PMID 21931733, 2011). "A study comparing 25 CHARGE subjects with CHD7 mutations to a large cohort of subjects with 22q11.2 deletion syndrome, noted that features found more commonly in CHARGE syndrome included coloboma, choanal atresia, facial nerve palsy, tracheoesophageal fistula, and genital hypoplasia in boys." (PMID 21995344, 2011). "There may be small intragenic deletions or mutations in the upstream regulatory region of the CHD7 gene, or it is possible that a different gene responsible for other syndromes with similar phenotypes as CHARGE syndrome may be involved." (PMID 21931733, 2011). "Since genetic analysis of the CHD7 gene has rarely been performed in previous reports dealing with ear abnormalities, the genotypic spectrum of CHD7 mutations was analyzed in deaf patients with CHARGE syndrome, and the clinical considerations concerning auditory rehabilitation were investigated." (PMID 21931733, 2011). "CHD7 mutation analysis has been suggested for KS patients with CHARGE syndrome-like features." (PMID 21682876, 2011). "In addition, mutations in CHD7, underlying over 60% of CHARGE syndrome (coloboma, heart defects, choanal atresia, retarded growth and development, genital abnormalities, and ear anomalies; MIM# 214800), have also shown to cause KS." (PMID 21682876, 2011). "CHD7 mutations were identified in 8 of 9 patients showing characteristics of CHARGE syndrome." (PMID 21931733, 2011). "Moreover, arhinencephaly and semicircular canal agenesis were two constant features in fetuses with CHARGE syndrome and CHD7 mutations." (PMID 16959034, 2006). "CHARGE syndrome may also be considered due to its multisystem involvement, particularly with genital and renal anomalies; however, it is usually characterized by coloboma, choanal atresia, and mutations in the CHD7 gene." (PMID 40843254, 2025). "However, the variant p.G1684S has been widely associated with CHARGE syndrome.The other two variants are novel truncating CHD7 variants reporting as de novo inheritance, a form of which was frequently identified in CHARGE syndrome than the other atypical CHARGE features." (PMID 39285472, 2024). "While these data support conserved microgyria due to CHD7 disruption across mouse and humans, additional investigation of human brain samples from patients with confirmed CHD7 mutations in the future will be required to confirm its significance in CHARGE syndrome." (PMID 34588434, 2021). "Interestingly, mutations in CHD7 have also been found in patients with KS, suggesting that both CHARGE syndrome and KS might share common genetic determinants and causes." (PMID 33869187, 2021). "They observe sensorineural hearing loss and demonstrate that CHD7 controls the expression of stress pathway components, which could help to explain how CHD7 haploinsufficiency causes changes in the ear associated with CHARGE syndrome." (PMID 34732824, 2021). "Whole exome sequencing (WES) was performed again, and coding regions of CHD7 (chromodomain-helicase-DNA-binding protein 7) were screened for mutations, which showed a de novo mutation deep in the intron (c.5405-17G>A), which confirmed the diagnosis of CHARGE syndrome." (PMID 30176936, 2018). "CHARGE syndrome is characterized by Coloboma, Heart defects, Atresia of the choanae, Retardation of growth and development, Genital hypoplasia and Ear abnormalities, and approximately 60–70% of the patients have pathogenic mutations in CHD7, the major causative gene of this syndrome." (PMID 29434620, 2018).
CHARGE syndrome (continued). "Also, genetic disorders such as CHARGE syndrome support the hypothesis of common genetic risk factors for ASD given that CHARGE syndrome is due to mutations in CHD7, which is a homolog of CHD8, one of the most recurrently affected genes in autism cohorts." (PMID 25136320, 2014). "Therefore, it has been hypothesized that IHH/KS represents a milder allelic variant of CHARGE syndrome, which has been supported by the identification of heterozygous CHD7 mutations in nICH/KS individuals." (PMID 24065959, 2013). "Therefore, we hypothesize that in CHARGE syndrome, besides mutations in CHD7, mutations in one or more additional and hitherto unknown genes are involved in the pathogenesis of this disease." (PMID 23285124, 2012). "Genetic analysis is especially important in CHARGE syndrome considering that this disorder shares many features with other syndromes which may lead to incorrect diagnosis and that some patients with mutations in the CHD7 gene manifest only mild symptoms as seen in familial cases of CHARGE syndrome." (PMID 21931733, 2011). "This might in turn reveal how CHD7 functions, and help illuminate the causes of CHARGE syndrome." (PMID 20041201, 2009). "CHD7 is considered responsible for CHARGE syndrome, an autosomal dominant condition characterized by multiple congenital anomalies." (PMID 41596295, 2026). "Our data provide a resource for further investigation of molecular mediators of CHD7 and a template to reveal functionally relevant therapeutic targets to alleviate specific aspects of CHARGE syndrome." (PMID 41664627, 2026). "Several genetic studies have reported on families with children who had CHARGE syndrome-like features but normal CHD7 genes." (PMID 40954203, 2026). "The diagnosis of CHARGE syndrome should be considered and confirmed through CHD7 gene sequencing in fetuses with esophageal atresia suspected by prenatal ultrasound, especially when combined with multiple malformations and feeding difficulties post-birth." (PMID 41210246, 2025). "Together, these results indicate that the chromatin compaction function of CHD7 exists in distinct genomic contexts and cell lines, including the cell type of origin of CHARGE syndrome." (PMID 40211002, 2025). "The majority of CHARGE syndrome cases result from haploinsufficiency of CHD7, a chromatin remodeling protein." (PMID 40988739, 2025). "De novo loss-of-function mutations of the chromodomain helicase DNA-binding protein 7 gene (CHD7) result in CHARGE syndrome." (PMID 40801603, 2025). "For example, CHARGE syndrome driven by CHD7, and Kabuki syndrome driven by MLL2/KMT2D/KDM6A both demonstrate fetal ear developmental abnormalities." (PMID 41020230, 2025). "A more complicated example was infant 1253290 with LP genotypes for both CHD7-CHARGE syndrome (prevalence 8/100,000 births; infant mortality rate 20%) and NODAL-Heterotaxy 5 (prevalence 1/100,000 births; infant mortality rate 23%; SUID PRR 15.1)." (PMID 41358299, 2025). "In Case #1, disruption of CHD7 confirmed the diagnosis of CHARGE syndrome in a patient with characteristic clinical features." (PMID 40692712, 2025). "MOs have been instrumental in exploring gene functions in zebrafish, such as the role of chd7 in CHARGE syndrome." (PMID 39336755, 2024). "Involvement of the olfactory bulbs is typically associated with CHARGE syndrome (OMIM #214800), another epigenetic disorder caused by mutations in CHD7 gene (OMIM *608892)." (PMID 39294711, 2024). "This suggests that CHD7 and its downstream genes are possibly crucial in the development of cardiac defects in CHARGE syndrome." (PMID 38892128, 2024). "This phenotypic variability appears in both humans with CHARGE syndrome and chd7 mutant zebrafish, among individuals with the same or different mutations." (PMID 39336755, 2024). "Kis is the homolog of CHD7 and CHD8, both of which are implicated in neurodevelopmental disorders including CHARGE Syndrome and autism spectrum disorders, respectively." (PMID 39125997, 2024).
CHARGE syndrome (continued). "Chd7 heterozygous mice show various signs of CHARGE syndrome, including growth retardation and severe head bobbing, destruction of the lateral semicircular canals, septal defects, and genital abnormalities." (PMID 38892128, 2024). "In GER (CD−M3), Tecta, Pcdh15, and Cdc14a were associated with NSHL, Slitrk6 with deafness and myopia, Pcdh15 with Usher syndrome, Eya1 with branchiootorenal syndrome, Chd7 with CHARGE syndrome, and Cdc14a with hearing impairment and infertile male syndrome." (PMID 39684410, 2024). "Our findings provide a potential mechanism to explain the aetiology of CHARGE syndrome where the Chd7 gene itself is unperturbed." (PMID 39418292, 2024). "In Xenopus, Chd7 mutant embryos have reduced Sox9, Twist1, and Snai2 expression and display CHARGE syndrome-like features." (PMID 39418292, 2024). "We detected a predominantly hypermethylation profile; the highest percentage of overlap in DMPs was with BAFopathies (11%, including ARID1A, ARID1B, SMARCB1, SMARCA2, SMARCA4), and CHARGE syndrome (10%, CHD7)." (PMID 38351292, 2024). "These complexities are especially evident in CHARGE syndrome (MIM# 214800), a genetic disorder mainly linked to mutations in the CHD7 gene." (PMID 39336755, 2024). "As PHOX2B is involved in neural crest development, similar to CHD7, the loss of PHOX2B function can lead to respiratory issues resembling those in patients with CHARGE syndrome." (PMID 38892128, 2024). "Aberrations in CHD7, an ATP-dependent eukaryotic enzyme attributed to the CHD family whose structure is homologous to that of CHD1L, have been confirmed to cause CHARGE syndrome, where “G” represents genital and urinary abnormalities." (PMID 39342328, 2024). "In mice, Chd7 heterozygotes present with CHARGE syndrome-like features and trunk neural crest cells require Chd7 to maintain their multipotency." (PMID 39418292, 2024). "Considering these clinical similarities, the current study utilized a previously established CRISPR-based chd7 knockout zebrafish model of CHARGE syndrome to assess the potential overlap between these two neurocristopathies." (PMID 37239446, 2023). "The causes were autosomal recessive non-syndromic hearing loss (GJB2), Townes–Brocks syndrome (SALL1), Pendred Syndrome (SLC26A4), Chromosome 8P inverted duplication and deletion syndrome, and CHARGE syndrome (CHD7)." (PMID 36675424, 2023). "Impaired CHD7 observed in CHARGE syndrome affected the BRG1 expression and chromatin remodeling of rRNA genes." (PMID 38139171, 2023). "Previous studies also have shown that heterozygous chd7 mice exhibit multiple symptoms of CHARGE syndrome, such as ocular defects, impaired vestibular sensation, and inner ear damage." (PMID 37686337, 2023). "CHARGE syndrome exhibited a ~7% overlap with the JARID2 cohort, and it is caused by variants in CHD7, characterized by multiple congenital anomalies." (PMID 37762546, 2023). "CHARGE syndrome, a differential to RERE-related disorders, indicated to involve both NDDs and CAs, is reported to be caused by de novo mutations in the CHD7 gene with a prevalence of 1 in 10,000 births." (PMID 36383254, 2023). "Genetic causes included autosomal recessive non-syndromic hearing loss (GJB2/connexin 26), Townes–Brocks syndrome (SALL1), Pendred syndrome (SLC26A4) and Chromosome 8P inverted duplication and deletion syndrome, and CHARGE syndrome (CHD7)." (PMID 36675424, 2023). "Among the 45 excluded patients, there were 5 cases of DiGeorge syndrome, 5 cases of PWS, and 2 cases of CHARGE syndrome due to the CHD7 gene." (PMID 38093364, 2023). "By modeling CHARGE syndrome in inner ear organoids derived from these cell lines, we demonstrate that CHD7 plays critical roles in otic lineage specification and hair cell generation." (PMID 36396635, 2022). "Pathogenic variants in the chromatin remodeling factor CHD7 are the most common cause of CHARGE syndrome, accounting for approximately 70%–90% of CHARGE syndrome cases." (PMID 36172288, 2022).